MPO (myeloperoxidase)
Diseases named in the same sentence as MPO in open-access papers (continued):
Sharing a sentence is not in itself a finding about the gene and the disease.
colitis (continued). "The results showed that deoxycholic acid treatment alleviated the symptoms of colitis, reduced the migration of MPO-positive neutrophils into the colonic tissue, and reduced the infection of C. jejuni." (PMID 36713373, 2022). "Evaluations in colitis mice showed that the treatment significantly alleviated the symptoms of colitis by decreasing the local level of myeloperoxidase (MPO) and the disease activity index (DAI) score in mice." (PMID 36440435, 2022). "Previous studies have shown that niacin attenuates the severity of colitis by decreasing colonic MPO activity, TNF-α, and VEGF levels in a guinea pig model." (PMID 35955466, 2022). "Obviously, the use of BD-1 and BD-1 + Ceftri in early life reduced inflammation scores and MPO activity levels, relieved inflammatory symptoms, and partially protected colonic mucosal structures when long-term colitis occurred." (PMID 35935215, 2022). "PSG significantly reduced the colonic inflammation by reversing the levels of myeloperoxidase, diamine oxidase activity, iNOS, and COX2 and strengthened the intestinal barrier by increasing the expressions of ZO1, occludin, and MUC2 of IBD mice." (PMID 36017235, 2022). "In this study, BEY treatment enhanced antioxidant activities as indicated by a remarkable reduction in MPO activity in TNBS-induced colitis." (PMID 35565934, 2022). "The anti-inflammatory effect of R. intestinalis on colitis was also verified by MPO staining of colon tissue." (PMID 35893896, 2022). "Previous reports on blockade of NLRP3 with this specific NLRP3 inhibitor effectively limited the induction of DSS colitis in mice, and inhibits NF-κB, IL-1β, caspase-1 and MPO activity." (PMID 35693797, 2022). "In rats with TNBS-induced colitis, MPO activity got its maximum on days 7 and 10 post-induction and was consistent with the up-regulation of MMP-9 in peripheral and colonic neutrophils which modulates transmural colonic damage." (PMID 35766160, 2022). "The MPO analysis showed a 53% increase in the vehicle-treated colitis group compared with the naive (p < 0.05)." (PMID 35295931, 2022). "Oral administration of NK151, NK175, or their (4:1) mix suppressed cGm-induced colitis in mice: they suppressed colonic myeloperoxidase activity, IL-1β and IL-6 expression, and the NF-κB+CD11c+ cell population, while significantly increasing IL-10 expression." (PMID 35631220, 2022). "In the mice with acetic acid-colitis, CPn reduced the peritoneal granulocyte adhesion, intestinal tissue injury, ROS production, and MPO expression." (PMID 35399093, 2022). "Colitis was defined by assessing weight loss, colonic length, histological score, TNF-α levels, nitric oxide levels, cyclic adenosine monophosphate levels, MPO activity, and inducible nitric oxide synthase gene expression in colonic tissue." (PMID 35239781, 2022). "It suppressed the inflammatory response via the attenuation of TNF-α, IL-1β, IL-6, and MPO activity in colitis rats in TNBS-induced colitis." (PMID 36235004, 2022). "Similar to the acute colitis model, body weight loss was reduced in the primed group, which also had lower DAI scores and MPO activity." (PMID 36076306, 2022). "Colitis induction in untreated rats caused necrotic effects in colon tissues, a significant increase in colonic IL-1β, TNF-α, MPO, and MDA levels, and a remarkable decrease in GSH and TAC levels in colon tissue in comparison to the control group." (PMID 35428860, 2022). "The results showed that butyric acid treatment alleviated the symptoms of colitis, reduced the migration of MPO-positive neutrophils into the colonic tissue, and similarly reduced the infection of C. jejuni." (PMID 36713373, 2022). "The secretion of NO and TNF-α and the accumulation of MPO were also decreased by piperine in colon tissue of mice with acetic acid-induced colitis." (PMID 35807865, 2022).
colitis (continued). "Chlorogenic acid seems to improve inflammation of colitis mice models, reducing NF-κB and myeloperoxidase, reducing oxidative stress and apoptosis markers, and lowering pro-inflammatory cytokines." (PMID 35056616, 2022). "Accordingly, in rats with methotrexate-colitis, supplementation of CPn reduced the intestinal barrier permeability, bacterial translocation, MPO expression, and intestinal water content." (PMID 35399093, 2022). "As neutrophils play a key role in C. jejuni-induced colitis, we used immunohistochemistry to assess the status of MPO-positive neutrophil infiltration in colonic tissue." (PMID 36713373, 2022). "Lastly, another study reported that quercetrin reduced the progression of colitis in rats by decreasing MPO (myeloperoxidase) and iNOS levels." (PMID 35415693, 2022). "The activity of Myeloperoxidase (MPO) in mice with colitis was significantly reduced after curcumin administration." (PMID 35795556, 2022). "In this study, we explored the prophylactical potential of BCP in DSS-induced colitis by evaluating changes in the gut microbiota, stool weight, digestive tract motility, colon length, colon histology, myeloperoxidase (MPO), and inflammatory mediators." (PMID 36431883, 2022). "This is the reason why we chose to measure PI3Kδ levels and use immunohistochemistry to detect MPO-positive neutrophil migration in colonic tissues as a basis for evaluating the severity of colitis." (PMID 36713373, 2022). "An increase in MPO activity, a biomarker of neutrophil infiltration, was found in the colitis group treated with the vehicle; however, the HEBD treatment reduced this inflammatory marker." (PMID 35295931, 2022). "At the end of the trial on day 46, we comprehensively analyzed inflammation scores, typical pathology section images, and MPO activity levels to determine the level of inflammation in DSS-induced colitis." (PMID 35935215, 2022). "In our study, SYD successfully inhibited the enhanced MPO activity in the colon of DSS-induced colitis mice." (PMID 33959000, 2021). "For example, oral supplementation of fermented soy germ (55% daidzein, 30% glycitein, and 15% genistein in aglycone forms for 15 days) to TNBS-induced colitis Wistar rats significantly suppressed colonic MPO compared to untreated animals." (PMID 33916612, 2021). "In experimental colitis, disease severity is often positively correlated with the levels of MPO activity and pro-inflammatory cytokines, such as TNF-α and IL-1β." (PMID 33967768, 2021). "It significantly aggravated colitis's clinical signs, including weight loss, DAI, colon length, colonic MPO activity, pathological changes, and goblet cell secretion." (PMID 34158863, 2021). "MPO activity serves as a marker for measuring neutrophil inflammatory response after colitis induction." (PMID 33530569, 2021). "We also measured the activity and expression of another NETs-related protein, MPO, which were elevated after the induction of colitis." (PMID 34884536, 2021). "Administration of FFAR4 agonist GSK137647 attenuated both TNBS-induced and DSS-induced colitis in mice, as indicated by macroscopic parameters and myeloperoxidase activity." (PMID 34444876, 2021). "As well, decreased levels of IL-1β, IL-6, IL-8, and TNF-α in the plasma, and decreased levels of IL-6 and TNF-α, and increased level of MPO in the colon were shown in mice with colitis treated by EGCG-FMT compared with other three groups." (PMID 34493333, 2021). "MPO, an oxidative stress-related enzyme found in neutrophils and other cells, can be used to quantitatively evaluate the severity of acute colitis and the efficacy of drugs in animal models of inflammation." (PMID 34641356, 2021). "HE ameliorated colitis in HFD mice by reducing colonic myeloperoxidase activity (by 2.3-fold), macrophage accumulation (by 2.6-fold) and mRNA expression of IL-6 (by 2.3-fold) in HFD mice." (PMID 34380504, 2021).
colitis (continued). "In contrast, MPO activity was significantly reduced in colon tissues from the CsAc-EAMP-treated group when compared with that in the untreated colitis group." (PMID 34575488, 2021). "Mice treated with pNAPE-LP showed a significant improvement of colitis in terms of histological damage score, macrophage count, and myeloperoxidase levels (−53, −82, and −70.4%, respectively)." (PMID 33986673, 2021). "In the present study, exposure to RS raised neuroinflammation and colitis: it induced IL-6 expression and NF-κB activation in the hippocampus and myeloperoxidase activity and NF-κB activation in the colon." (PMID 34391441, 2021). "A single intracolonic administration of UAMC-00050 increased colonic MPO activity, both in control and post-colitis animals." (PMID 34072320, 2021). "Induction of colitis by acetic acid led to significant increases in the activity of MPO enzyme compared to the control group (p<0.001)." (PMID 34745922, 2021). "The transplantation of FBp, FBi, or FN mitigated IS-induced colitis in mice: they alleviated IS-induced myeloperoxidase and TNF-α and IL-6 expression in the colon." (PMID 33731795, 2021). "In a preclinical study, intracolonic administration of a combination of HA and mesalamine promoted wound healing in colonic injuries and inhibited myeloperoxidase (MPO) activity in the inflamed colon tissue of rats subjected to TNBS-induced colitis." (PMID 35011688, 2021). "In the present study we showed that colitis induction significantly increased MPO, MCP-1, and MMP-9 levels in the colon tissue." (PMID 33995942, 2021). "The anti-inflammatory activity was documented in vitro as well as in the mouse model of DSS-induced colitis through macroscopic, stool, and microscopic scores, and MPO activity." (PMID 33803793, 2021). "Induction of colitis in mice pretreated with acrylamide resulted in an additional elevation in colonic MPO, MCP-1, and MMP-9 levels." (PMID 33995942, 2021). "Animals treated with 4% DSS in drinking water developed severe colitis, characterized by increased macroscopic colon damage score, reduced colon weight, and elevated MPO activity." (PMID 34444876, 2021). "Within the intestinal mucosa of colitis patients, neutrophils accumulate at inflamed regions and release MPO." (PMID 33946346, 2021). "The induction of colitis by TNBS instillation resulted in an approximately four-fold elevation in MPO activity compared to the control group (35,749.15 ± 4494.80 vs. 8958.17 ± 1448.31 μU/mg protein)." (PMID 34884536, 2021). "The increase in MPO levels due to increased infiltration of neutrophils is a well-established marker for monitoring the extent of inflammation during colitis condition." (PMID 34539597, 2021). "The results of this study revealed that administration of B. persicum essential oil reduced the activity of MPO enzyme in the colon tissue after induction of colitis with acetic acid." (PMID 34745922, 2021). "MPO is a marker of neutrophil infiltration, which has been observed to be activated in several experimental colitis models, including the DSS-induced colitis." (PMID 33505807, 2021). "Alteration in the abundance of genus Sutterella was positively correlated with pro‐inflammatory cytokines in colitis, whereas the change in Bifidobacterium was negatively correlated with histopathological score and MPO, especially induced by MP treatment." (PMID 33747442, 2021). "Both plant-derived AhR ligands, I3C and Q, diminished MPO expression in colitis mice to levels similar as found in healthy animals." (PMID 33668818, 2021). "Exposure to EC significantly induced colitis in mice: it induced colon shortening, myeloperoxidase activity, and TNF-α, IL-1β, and IL-6 expression in the colon." (PMID 33731795, 2021). "In contrast, the CsAc-EAMP-treated group showed significantly lower MPO levels than the untreated colitis group due to reduced immune cell infiltration and inflammation in colon tissues." (PMID 34575488, 2021).
colitis (continued). "The i.c. injection of TNBS resulted in reproducible colitis in mice, manifested by increased macroscopic colon-damage score and elevated MPO activity." (PMID 34444876, 2021). "Many studies have reported elevated MPO levels during colitis condition, wherein probiotic interventions had led to a decrease in the MPO activity that corresponded to a decrease in inflammation." (PMID 34539597, 2021). "Tiliroside (25.0 and 50.0 mg/kg) markedly alleviated the TNBS-induced colitis, evidenced by increased survival rate, longer colon length, decreased MPO activity, and ameliorated pathological changes of colons." (PMID 33868286, 2021). "Experimental colitis increased the activity of MPO and the levels of MCP-1 and MMP-9 as markers of inflammatory damage in the colonic tissue." (PMID 33995942, 2021). "The colitis untreated group in our study presented with significant elevation of colonic MPO activity, which indicates neutrophil infiltration and inflammatory cascade dysfunction, documented not only in animal models but also in IBD patients." (PMID 33441125, 2021). "Compared to the UC group, HE staining in the UCHM group and UCEA group indicated that colitis was relieved, the histopathological score and MPO were both significantly reduced, and the serum hs-CRP concentration was decreased significantly." (PMID 34659440, 2021). "Immunohistochemistry (IHC) of MPO revealed that DSS colitis significantly enhanced the hepatic neutrophil infiltration in these models." (PMID 34336855, 2021). "As an indicator for colitis extent, MPO can induce tissue damage due to the release of oxyradicals from leukocytes." (PMID 34046146, 2021). "An early marker of DSS-induced colitis is the infiltration of neutrophilic granulocytes that are characterised by the production of myeloperoxidase (MPO)." (PMID 33668818, 2021). "In comparison to DSS colitis group, the remarkable reduction in MPO levels was statistically significant in mice groups treated with surface proteins of NCFM (P < 0.01) and MTCC 5690 (P < 0.05), although not in MTCC 5689 group (P > 0.05)." (PMID 34539597, 2021). "MPO has been noted to mediate activation of neutrophils, the release of pro-inflammatory cytokines, and to gastrointestinal disease, such as colitis." (PMID 33920187, 2021). "These FMTs inhibited the RS-induced colitis: they decreased myeloperoxidase activity and IL-6 expression and suppressed NF-κB activation." (PMID 34391441, 2021). "Feeding animals with feed containing beta-glucans, regardless of their molar mass, reduced the colon concentration of MPO and accelerated remission of colitis." (PMID 33923129, 2021). "Garcinia combogia extract, previously used to study its effect in reducing MPO activity in colitis induced in rats as an oral delivery method, has shown progressive results." (PMID 33799680, 2021). "The MPO level was significantly higher in DSS-induced colitis mice, and this effect was inhibited by PSE and PLE." (PMID 34829556, 2021). "MPO is an enzyme in neutrophils whose activity indicates the severity of neutrophil infiltration and colitis." (PMID 34867317, 2021). "Reductions in MPO activity have also been reported in DSS-colitis BALB/c mice administered soybean β-conglycinin (50 or 500 mg/kg for 28 days) and transported tripeptide VPY (Val-Pro-Tyr, 2-week pretreatment of drinking water with 0.1 and 1 mg/mL)." (PMID 33916612, 2021). "Colitis induction significantly elevated MPO levels in all DSS-treated groups compared to corresponding controls (p < 0.001)." (PMID 33436730, 2021). "The measurement of MPO activity can indirectly reflect the strength of neutrophil infiltration; thus, it can be used as a quantitative index of inflammation in colitis." (PMID 33959000, 2021). "EVs derived from MSCs showed a proper therapeutic effect in a rat colitis model by decreasing myeloperoxidase (MPO) activity, malondialdehyde (MDA) and apoptosis (caspase-3, caspase-8 and caspase-9)." (PMID 34359898, 2021).
colitis (continued). "Oral gavage of vancomycin or ampicillin significantly deteriorated tIsc-induced colitis; they dramatically increased colon shortening, myeloperoxidase activity, and TNF-α and IL-1β levels in the colon." (PMID 33324357, 2020). "In rats with methotrexate-induced or oxazolone-induced colitis, MPO activity was suppressed by RES administration." (PMID 32722619, 2020). "Through their myeloperoxidase (MPO) activity, neutrophils migrate into the lamina propria of DSS‐induced colitis causing oxidative‐induced tissue damage and other detrimental effects." (PMID 32410383, 2020). "KM1608 significantly attenuated the disease activity of dextran sodium sulfate-induced colitis in mice and suppressed inflammatory mediators such as myeloperoxidase, proinflammatory cytokines (TNF-α and IL-6), and the Th2-type cytokine IL-4 in the colon." (PMID 32927852, 2020). "RG and fRG also alleviated the EC- or IS-induced colitis in mice; they suppressed the EC-induced myeloperoxidase activity, NF-κB activation, and TNF-α and IL-6 expression, and NF-κB+/CD11c+ cell population in the colon." (PMID 32224881, 2020). "The effects of DSC on colonic neutrophils were further confirmed by colonic MPO activity in DSS‐colitis mice." (PMID 32945118, 2020). "The results of this study suggested that in the OXZ-colitis model group, iNOS expression and NO release were increased, and NO and iNOS were positively correlated with MPO activity." (PMID 33237174, 2020). "MPO activity of the colitis group (75.00 ± 37.80 μU/mg) recorded the highest value, whereas that of colitis + 5-ASA (38.69 ± 15.95 μU/mg) and colitis + TOE (23.34 ± 6.02 μU/mg) decreased." (PMID 33092149, 2020). "Sinapic acid treatment also significantly decreased MPO accumulation and reduced inflammation scoring in colitis mice." (PMID 33312339, 2020). "In the present study, we found that colonic MPO activity in DSS-induced colitis mice was drastically increased as compared with the control mice, whereas the MPO activities in uvaol group were significantly suppressed." (PMID 32411289, 2020). "By contrast, DNase I treatment significantly decreased the presence of MPO-DNA complexes in the colon homogenates of mice with DSS-induced colitis." (PMID 32764411, 2020). "prausnitzii also reduced MPO activity in a model of inflammatory bowel disease with chronic mild/severe grade colitis, thus highlighting the ability of F. prausnitzii to reduce neutrophil activation in this context." (PMID 32985332, 2020). "SLBZS treatment significantly reduced MPO activity in DSS-induced colitis mice and increased MPO activity in the model group." (PMID 32547403, 2020). "Drinking water with soybean-derived tripeptide VPY can reduce DAI, weight loss, MPO activity, and expressions of IL-1β, IL-6, IL-17, IFN-γ, and TNF-α in colitis mice, suggesting that VPY can treat IBD." (PMID 32963495, 2020). "Rats with DNBS-induced colitis showed a marked increase in colonic MPO levels (35 ± 8.6 ng/mg tissue) compared to the control animals (2.8 ± 0.5 ng/mg tissue)." (PMID 32575844, 2020). "Sacral nerve stimulation promoted recovery of colitis demonstrated by decreased disease activity index, myeloperoxidase activity, tissue TNF‐alpha, and histological scores as well as an increased colonic M2 macrophage population." (PMID 31925899, 2020). "Further, we earlier demonstrated a role for neutrophil-derived MPO in murine experimental colitis, with significant attenuation of disease via pharmacological inhibition of MPO." (PMID 32899436, 2020). "Free F96 treatment significantly lower the MPO activity in the colitis mice as compared with those in the untreated colitis mice." (PMID 35519029, 2020). "In this study, the concomitant application of HnAb reduced the intestinal inflammatory damage induced by DSS, assessed by the colitis score, MPO expression and the expression levels of the cytokines IL-1β, IFN-γ, TNF-α in colonic tissues." (PMID 33193406, 2020).